IGFALS (insulin like growth factor binding protein acid labile subunit)
Description:
Involved in protein-protein interactions that result in protein complexes, receptor-ligand binding or cell adhesion.
Synonyms: ALS; ACLSD
Tractability: Antibody: its Gene Ontology location is reachable by antibodies, with high confidence; UniProt places it where antibodies can reach, with medium confidence; UniProt predicts a signal peptide or a membrane-spanning region. PROTAC: its protein half-life has been measured.
Gene: Protein-coding gene on chromosome 16 (1,790,413 to 1,794,971, reverse strand). Ensembl gene ENSG00000099769.
Subcellular location: Secreted, extracellular space
Pathways (Reactome):
Metabolism of proteins: Regulation of Insulin-like Growth Factor (IGF) transport and uptake by Insulin-like Growth Factor Binding Proteins (IGFBPs)
Gene Ontology:
Molecular function: insulin-like growth factor binding; signaling receptor activity
Biological process: signal transduction
Cellular component: extracellular exosome; insulin-like growth factor ternary complex; extracellular region; non-collagenous component of interstitial matrix
Genetic constraint (gnomAD): Loss-of-function variants: 2 observed, 1.62 expected, observed/expected ratio (o/e) 1.24, 90% interval 0.42 to 1.91. That is too few expected variants to judge how well the gene tolerates losing a copy. Missense variants: 996 observed, 759.3 expected, observed/expected ratio (o/e) 1.31, 90% interval 1.24 to 1.38. Synonymous variants: 519 observed, 384.02 expected, observed/expected ratio (o/e) 1.35, 90% interval 1.26 to 1.45.
Homologues: Orthologues: chimpanzee IGFALS (99% identical), macaque IGFALS (94% identical), pig IGFALS (82% identical), guinea pig IGFALS (78% identical), mouse Igfals (78% identical), rat Igfals (78% identical), dog IGFALS (76% identical), tropical clawed frog igfals (58% identical), zebrafish igfals (51% identical). Paralogues in human: LRRC32 (27% identical), TLR3 (27% identical), TLR7 (26% identical), TLR8 (25% identical), NRROS (24% identical), TLR5 (22% identical), CD180 (21% identical), TLR4 (18% identical), VASN (17% identical), RXFP1 (17% identical), TSKU (17% identical), RXFP2 (16% identical), and 10 more.
Diseases named in the same sentence as IGFALS in open-access papers:
IGFALS is named in the same sentence as 43 diseases in open-access papers, as found by Europe PMC text mining. Sharing a sentence is not in itself a finding about the gene and the disease. The quoted sentences say what the papers report.
Insulin resistance (5 papers, 2018 to 2025). Increased resistance towards insulin, that is, diminished effectiveness of insulin in reducing blood glucose levels. "Biallelic mutations in IGFALS may also be associated with insulin resistance." (PMID 30302116, 2018). "This is consistent with the product of IGFALS (acid-labile subunit) increasing the serum half-life of IGF-1, and patients with IGFALS deficiency present with IGF-1 deficiency and insulin resistance." (PMID 40065360, 2025). "IGFALS is also a plasma protein synthesized by the liver, and it improves glucose tolerance and insulin resistance by prolonging the half-life and increasing the circulating concentration of insulin-like growth factor-1." (PMID 35745003, 2022). "Insulin resistance-associated factors, such as IGF1 and IGFALS, and inflammation-related factors, such as CSF1 and TGFβ2, were all highly enriched in the MetS group." (PMID 32133283, 2020).
breast carcinoma (4 papers, 2006 to 2019). "The down-regulated IGFALS was associated with etiology and progression of breast cancer, prostate cancer and testicular germ cell tumors, and it was identified to function as a tumor suppressor in liver cancer." (PMID 30733650, 2019). "Previous studies on polymorphisms/haplotypes in IGFI, IGFBP3 and IGFALS and their association to breast cancer susceptibility and circulating levels of both IGFI and IGFBP3 have been reported making them interesting targets in mammographic density studies." (PMID 20302654, 2010).
COVID-19 (4 papers, 2021 to 2022). A disease caused by infection with severe acute respiratory syndrome coronavirus 2. "Reduced circulating levels of IGF1 or IGFALS were found to be associated with COVID-19 mortality or in severe COVID-19 patients with adverse prognosis in two separate studies." (PMID 35958562, 2022). "The ability of CHI3L1 and IGFALS to discriminate favorable and adverse prognosis in COVID-19 patients was superior to that of the existing biomarkers." (PMID 34667241, 2021). "This study also demonstrated the reduction of IGFALS levels in severe COVID-19 patients with adverse prognosis." (PMID 34667241, 2021). "Subsequent statistical analysis using ROC curves found that two putative prognostic indicators, namely CHI3L1 and IGFALS, may be useful in severe COVID-19 patients." (PMID 34667241, 2021). "However, the regulatory mechanisms of IGFALS and IGF-1 in COVID-19 remain elusive, and further studies are needed to determine the functional roles of both proteins in the pathogenesis of the disease." (PMID 34667241, 2021).
hepatocellular carcinoma (4 papers, 2022 to 2025). A malignant tumor that arises from hepatocytes. "IGFALS, crucial for the stability of circulating insulin growth factors, is down-regulated in hepatocellular carcinoma and associated with poor prognosis." (PMID 41155404, 2025). "Additionally, the reduced expression of HAO2 and IGFALS has been suggested as a potential prognostic and diagnostic marker for hepatocellular carcinoma (HCC)." (PMID 38992651, 2024). "As a liver tissue-specific gene, the down-regulation of the expression of IGFALS suggested a poor prognosis of hepatocellular carcinoma." (PMID 36582223, 2022). "Our data revealed a decrease in the expression of IGFALS in patients with alcoholic liver fibrosis, as shown in HBV‐related hepatocellular carcinoma (HCC)." (PMID 36582223, 2022).
Stroke (3 papers, 2010 to 2024). Sudden impairment of blood flow to a part of the brain due to occlusion or rupture of an artery to the brain. "In addition, the expression level of IGFALS was linked to coronary heart disease or stroke among postmenopausal women." (PMID 30733650, 2019).
asthma (2 papers, 2024 to 2025). "In addition, our group has previously shown changes associated with asthma in the serum levels of many of the proteins detected in urine, i.e., IGFALS, FCN2, HSPG2, CD26/DPP4, and CD14, and suggested their use as potential phenotype/severity biomarkers of this disease." (PMID 39858454, 2025).
diabetes (2 papers, 2022 to 2025). "Although IGF1, IGFBP3, and IGFALS may be associated with diabetes, the levels of these proteins in our study in severe patients without diabetes were also very low, indicating that their decline was not only due to diabetes." (PMID 35958562, 2022).
liver disease (2 papers, 2022 to 2024). "Despite the fact that transcriptional analysis of liver IGFALS to examine its role in liver diseases is rarely performed, IGFALS forms ternary complexes with IGF-I and IGFBP3 in the circulation and regulates body growth, development, and other physiological/pathophysiological processes." (PMID 36582223, 2022).
autism (1 paper, 2015). Persistent deficits in social interaction and communication and interaction as well as a markedly restricted repertoire of activity and interest as well as repetitive patterns of behavior. "The patient showed all the typical features of Autism, WES revealed a de novo frameshift mutation in CREBBP and de novo sequence variants in TNC and IGFALS genes." (PMID 25768348, 2015).
deep vein thrombosis (1 paper, 2025). "Due to the low number of events, no meaningful conclusions could be drawn regarding the association between IGFALS dynamics and other adverse outcomes, including postoperative deep vein thrombosis (n = 3), pulmonary embolism (n = 2), and mortality (n = 0)." (PMID 40864735, 2025).
depression (1 paper, 2025). "More pronounced depression in serum IGFALS is associated with poorer recovery outcomes." (PMID 40864735, 2025).
dermatitis (1 paper, 2024). An inflammatory process affecting the skin. "Unexpectedly, a significant relationship between dermatitis and the levels of certain insulin-biosynthesis-and-secretion- or insulin-resistance-related polypeptides (GSTO1, FETUA, GSTP1, IGFALS or LDHA) was observed." (PMID 39062477, 2024).
endometrial cancer (1 paper, 2020). Primary or metastatic malignant neoplasm involving the endometrium (mucous membrane that lines the endometrial cavity). "A third smaller, but distinctly separate, network of IL13, IL21, ANKAR, CAPS, and IGFALS was associated with Wnt and VEGF signaling, and are likely associated with environmental cues in high-grade endometrial cancer." (PMID 32471032, 2020).
gastric cancer (1 paper, 2022). A primary or metastatic malignant neoplasm involving the stomach. "IGFALS has also been identified as a tumor suppressor gene, which is silenced by methylation in HCC, and IGFALS was associated with disease-free survival of gastric cancer." (PMID 36428813, 2022).
heart failure (1 paper, 2025). Inability of the heart to pump blood at an adequate rate to meet tissue metabolic requirements. "This aligns with prior evidence linking IGFALS to non-valvular atrial fibrillation, heart failure, and recovery trajectories." (PMID 40864735, 2025).
influenza (1 paper, 2022). An acute viral infection of the respiratory tract, occurring in isolated cases, in epidemics, or in pandemics; it is caused by serologically different strains of viruses (influenzaviruses) designated A, B, and C, has a 3-day incubation period, and usually lasts for 3 to 10 days. "The protein IGFALS, which distinguishes severity of WNV infection, facilitates ubiquitination of signaling mediators IRAK1 and TRAF6 to inhibit influenza viral replication and has recently been shown to be a sensitive biomarker of COVID-19 infection." (PMID 36569838, 2022).
ischemic stroke (1 paper, 2023). A stroke disorder caused by obstruction of blood flow to the brain, due to thrombotic (local blood clot formation) or embolic (due to a blood clot or other material traveling from another site) event. "IGFALS is significantly increased in non-valvular atrial fibrillation expression, which may increase the risk of ischemic stroke." (PMID 36959823, 2023).
Obesity (1 paper, 2024). Accumulation of substantial excess body fat. "Alternatively, in addition to the IGF/IGFBP/IGFALS ternary complex, MMP2 can cleave COL6A3 to generate endotrophin, which is associated with onset of obesity-related metabolic disorders." (PMID 38645061, 2024).
osteoporosis (1 paper, 2020). A condition of reduced bone mass, with decreased cortical thickness and a decrease in the number and size of the trabeculae of cancellous bone (but normal chemical composition), resulting in increased fracture incidence. "There was also a significant decrease in expression of IGFALS and decreased expression of IGF, and its binding proteins in serum have been linked with increased adipogenic potential of mesenchymal stem cells over osteogenic potential in osteoporosis." (PMID 32157596, 2020).
progeria (1 paper, 2024). "The volcano plot showed a significant number of upregulated proteins in progeria compared with young donors, including serotransferrin (TF), spectrin alpha chain (SPTA1), insulin-like growth factor-binding protein complex acid labile subunit (IGFALS), and others." (PMID 38141925, 2024).
Short stature (1 paper, 2015). A height below that which is expected according to age and gender norms. "Monogenic causes of short stature which are associated with a low serum IGF-I level and normal or high GH levels could comprise the defects of GH1 (bioinactive GH), GHSR (ghrelin receptor), GHR (GH receptor), STAT5B, IGF1, and IGFALS." (PMID 26777041, 2015).
thyroid (1 paper, 2021). "Finally, we found rs1912998 regulates the expression of IGFALS (P = 1.70E-06) and HAGH (P = 5.08E-07) in thyroid, which is significantly related to thyroid cancer." (PMID 33614667, 2021).
tumor (5 papers, 2015 to 2025). "Our results also confirm previous findings showing IGFALS as a possible tumor-suppressor gene silenced by methylation in HCC." (PMID 25945129, 2015). "IGFALS has been reported to function as a tumor suppressor in HCC." (PMID 35629368, 2022).
infection (1 paper, 2023). The state of being infected such as from the introduction of a foreign agent such as serum, vaccine, antigenic substance or organism. "However, using receiver operating characteristic curves, we identified four to 48 candidate biomarkers of infection depending on the pathogen, including seven overlapping biomarkers (DSG2, PCBP1, MGAM, APOA4, DPEP1, GOT1, and IGFALS)." (PMID 38193073, 2023). "infections; APOA4, DPEP1, and GOT1 were negative predictors while IGFALS was a positive predictor." (PMID 38193073, 2023).
skeletal dysplasia (1 paper, 2024). Any Mendelian diseases that affects growth and development of the skeleton. "Together, these data indicate that low IGF-1, IGFBP3, and IGFALS levels likely contribute to growth retardation and skeletal dysplasia in Tmem263-KO mice." (PMID 38241182, 2024).
IGFALS also shares sentences with these, for which no sentence is quoted: cancer (2 papers); prostate carcinoma (2); Sepsis (2); acute kidney injury (1); allergic asthma (1); brain tumors (1); cholestasis (1); coronary heart disease (1); heart disease (1); hyperlipidemia (1); Hypertension (1); liver cancer (1); liver fibrosis (1); malignant brain tumors (1); metabolic disorders (1); pulmonary embolism (1); testicular germ cell tumor (1); thyroid cancer (1).